APLN (apelin)
Diseases named in the same sentence as APLN in open-access papers (continued):
Sharing a sentence is not in itself a finding about the gene and the disease.
colorectal adenocarcinoma (1 paper, 2019). The most common type of colorectal carcinoma. "Apelin, and its receptor mRNA, and protein expression levels were measured in tumor tissue of 56 surgically treated colorectal adenocarcinoma (CRC) patients." (PMID 31547096, 2019).
Crohn disease (1 paper, 2018). A gastrointestinal disorder characterized by chronic inflammation involving all layers of the intestinal wall, noncaseating granulomas affecting the intestinal wall and regional lymph nodes, and transmural fibrosis. "Accordingly, apelin was shown to be highly expressed in the mesenteric adipose tissue of Crohn's disease patients." (PMID 30369924, 2018).
cutaneous leishmaniasis (1 paper, 2024). Leishmaniasis affecting the skin. "Further research is required to explain the precise mechanisms by which apelin influences the immune response in cutaneous leishmaniasis and to explore its prospective role in targeted therapies." (PMID 39767230, 2024). "The objective of this study was to investigate the relationship between serum levels of specific biomarkers, such as presepsin, apelin, and irisin, and the clinical features, location, number, and size of lesions in patients suffering from cutaneous leishmaniasis." (PMID 39767230, 2024).
cutaneous melanoma (1 paper, 2021). A primary melanoma arising from atypical melanocytes in the skin. "In conclusion, our results suggest that apelin signaling plays an important role in the pulmonary metastasis formation of cutaneous melanoma." (PMID 33707612, 2021). "Our results show that apelin promotes blood and lymphatic vascularization and the growth of pulmonary metastases of skin melanoma." (PMID 33707612, 2021). "We investigated the role of apelin signaling in the malignant behavior of cutaneous melanoma." (PMID 33707612, 2021).
diabetic angiopathy (1 paper, 2023). "The apelin–Apj system has been reported to have therapeutic potential for various vascular diseases, such as CVD and diabetic angiopathy, which have been observed in CKD patients." (PMID 36562292, 2023).
diabetic neuropathy (1 paper, 2023). A chronic, pathological complication associated with diabetes mellitus, where nerve damages are incurred due to diabetic microvascular injury involving small blood vessels that supply these nerves, resulting in peripheral and/or autonomic nerve dysfunction. "However, further investigations will be required to determine the potential effects of apelin in diabetic neuropathy." (PMID 37636297, 2023).
diaphragmatic hernia (1 paper, 2023). A congenital or acquired weakness or opening in the diaphragm which allows abdominal contents to protrude into the chest cavity; congenital diaphragmatic hernias are caused when the embryonic diaphragm fails to fuse. "Our gene ontology analysis also shows that nitrofen-exposed microvascular endothelial cells are enriched in apelin signaling in the absence of lung compression from an ipsilateral diaphragmatic hernia." (PMID 37330615, 2023).
dyslipidaemia (1 paper, 2020). "Furthermore, a recent study in a rat model showed that apelin improved dyslipidaemia by decreasing TC, TG and LDL-C, and increasing HDL-C concentration." (PMID 32998691, 2020).
endotoxemia (1 paper, 2018). "Thus, apelin appears to be a potential therapeutic for endotoxemia-induced tissue injuries at multiple levels." (PMID 30061611, 2018).
experimental autoimmune encephalomyelitis (1 paper, 2024). An autoimmune demyelinating disease of the central nervous system that is produced experimentally in animals by the injection of homogenized brain or spinal cord in Freund's adjuvant. "Here, we show that treatment with apelin, a secreted peptide ligand for the G protein-coupled receptor APJ/Aplnr, is protective in experimental autoimmune encephalomyelitis (EAE), an animal model of MS." (PMID 39060233, 2024).
glaucoma (1 paper, 2021). Increased pressure in the eyeball due to obstruction of the outflow of aqueous humor. "Identified gene transcripts were involved in several pathways, some implicated in glaucoma before (e.g., TGF-β and neurotrophin signaling), whereas others are new (e.g., prolactin and apelin signaling)." (PMID 34156425, 2021).
glycogenosis (1 paper, 2024). "In liver, apelin exposure also promotes glycogenosis through the insulin signaling pathway, suggesting this response may be latent activity of DCA although hallmarks of excessive hepatic glycogen storage are no longer present at this point." (PMID 38764585, 2024).
gout (1 paper, 2021). A condition characterized by painful swelling of the joints, which is caused by deposition of urate crystals. "Interestingly, our KEGG analysis found that the different circRNAs in the gout group mainly participated in “FoxO signaling pathway,” “apelin signaling pathway,” and “cGMP-PKG signaling pathway,” except for the Toll-like receptor and NOD-like receptor signaling pathways." (PMID 34764979, 2021).
Granuloma (1 paper, 2023). A compact, organized collection of mature mononuclear phagocytes, which may be but is not necessarily accompanied by accessory features such as necrosis. "They observed that the expression level of the APJ receptor was higher in epithelial cancer cells than in granulosa cell tumours (granuloma, folliculoma); however, the opposite applies to apelin expression and secretion." (PMID 37238197, 2023).
head and neck cancer (1 paper, 2023). A primary or metastatic malignant neoplasm affecting the head and neck. "In head and neck cancer (HNC), serum APLN levels were significantly higher in patients than in the healthy controls; however, APLN was significant decreased after radiotherapy." (PMID 36614283, 2023).
hemangioma (1 paper, 2022). A benign vascular lesion characterized by the formation of capillary-sized or cavernous vascular channels. "However, specific biological functions of APLN have not been studied in IH and have potential value for further research as a novel biomarker of hemangioma." (PMID 35501731, 2022). "Finally, three genes (APLN, APLNR, TMEM132A) were identified as hub genes, which were consistently highly expressed in hemangioma tissues, regardless of different stages, through integrated WGCNA and PPI network analysis of DEGs." (PMID 35501731, 2022).
herpesvirus infection (1 paper, 2021). "Some important pathways, including neutrophil, antibacterial activities, primary lysosome, exogenous protein binding, the apelin signaling pathway, Kaposi sarcoma-associated herpesvirus infection, and the phosphatidylinositol signaling system, are involved in TB." (PMID 34803519, 2021).
Hypercholesterolemia (1 paper, 2020). An increased concentration of cholesterol in the blood. "In a clinical report previously published, the relationship between plasma cholesterol and apelin levels were reported in patients with hypercholesterolemia for whom lower apelin levels were determined." (PMID 32580404, 2020).
hypertriglyceridemia (1 paper, 2024). A laboratory test result indicating elevated triglyceride concentration in the blood. "Also, the authors observed that patients belonging to the highest apelin-12 quartile had a higher prevalence of hypertriglyceridemia, hypo-high-density lipoproteinemia, and MetS when compared with that seen in children belonging to the lowest quartile." (PMID 37930396, 2024).
Hypervolemia (1 paper, 2014). An increase in the amount of intravascular fluid, particularly in the volume of the circulating blood. "But, when results of our study are considered together with literature data; it may be speculated that hypervolemia that is prevalent in dialysis population causes elevations in apelin levels to maintain compensatory diuresis, increased cardiac contractility and vasodilation." (PMID 24433492, 2014). "Although patients with evident hypervolemia were excluded from the study; these relations which are present especially in the hypertensive group mark the relationship of apelin-36 with volume status." (PMID 24433492, 2014).
hypoadiponectinemia (1 paper, 2018). "The serum apelin level was significantly lower in the T2D rats, but significantly increased in T2D rats after infusion of apelin-transduced WJ-MSCs (P < 0.01) that reduced the risk of hypoadiponectinemia." (PMID 30526660, 2018).
idiopathic pulmonary arterial hypertension (1 paper, 2022). A sporadic form of pulmonary arterial hypertension (PAH) characterized by elevated pulmonary arterial resistance leading to right heart failure. "This study evaluated different apelin isoforms in PH patients and prospectively evaluated the role of apelin-17 in comparison with NT-proBNP and GDF-15 as diagnostic marker in idiopathic pulmonary arterial hypertension (IPAH)." (PMID 36685176, 2022).
influenza (1 paper, 2023). An acute viral infection of the respiratory tract, occurring in isolated cases, in epidemics, or in pandemics; it is caused by serologically different strains of viruses (influenzaviruses) designated A, B, and C, has a 3-day incubation period, and usually lasts for 3 to 10 days. "To test whether apelin treatment protects against influenza-induced lung vascular leakage, we administered exogenous apelin to infected WT and ECΔAhr mice." (PMID 37587341, 2023). "Taken together, these findings identify the apelin/APLNR signalling axis as a mechanism of AHR-dependent lung protection, preventing endothelial stress, vascular leakage, and epithelial remodelling, upon influenza-induced lung damage." (PMID 37587341, 2023).
joint disease (1 paper, 2012). "Serum ADMA and apelin levels and the 28-joint disease activity scores (DAS28) were assessed before and after 12 months of DMARDs treatment." (PMID 22927708, 2012).
kidney injury (1 paper, 2023). Trauma to the kidney. "While investigating determinants of serum apelin-13 level by multiple linear regression analysis in two different models, CRH, SAPS II, serum sodium, potassium, and the presence of kidney injury were independent predictors." (PMID 37510916, 2023).
Left ventricular dilatation (1 paper, 2019). Enlargement of the chamber of the left heart ventricle. "Experimental study demonstrated that apelin-knockout mice showed progressive and significant left ventricular dilatation and systolic dysfunction, which was attenuated by subcutaneous apelin infusion." (PMID 30872595, 2019).
liver cirrhosis (1 paper, 2017). "Recent clinical study demonstrates that the serum apelin level showed a significant relationship with the severity of liver cirrhosis in patients with chronic liver disease (CLD)." (PMID 29340118, 2017). "Apelin, diponectin and RBP4 levels are deregulated in liver cirrhosis depending on the degree of liver dysfunction." (PMID 29340118, 2017).
meningioma (1 paper, 2025). A generally slow growing tumor attached to the dura mater. "These represented pathways that may be amenable to drug targeting effective for both meningioma and VS and include apelin and G protein-coupled receptor signalling, calcium and neurotransmitter signalling, nitric oxide signalling, adherens junction remodelling, and vesicle transport." (PMID 41437121, 2025).
mental disorder (1 paper, 2018). A disease that has its basis in the disruption of mental process. "As a pair of biological active peptides, the role of apelin and APJ in the function of hypothalamus has been explored in many studies, and the changes of the apelin-APJ system in the stress-induced HPA axis dysfunction are also a study point in the mental disorders." (PMID 29751542, 2018).
metastasis (1 paper, 2019). The spread or migration of cancer cells from one part of the body (where they first appeared) to another. "The concentration of serum apelin level significantly increased in individuals with lymph node and distant metastasis." (PMID 31547096, 2019).
metastatic cancer (1 paper, 2024). A carcinoma which has spread from the original site of growth to another anatomic site. "In this review, we examined the impact of adipocytes on cancer by describing the adipocyte-secreted factors that are involved in controlling metastatic cancer, focusing on adipokines, such as adiponectin, leptin, visfatin, chemerin, resistin, apelin, and omentin." (PMID 38238841, 2024).
migraine (1 paper, 2022). "Neuropeptides directly associated with pain or migraine from significantly differentially expressed neuropeptide prohormone genes include apelin (APLN), cortistatin (CORT), IGF2, neuromedin B (NMB), neuropeptide W (NPW), PDGFA and platelet-derived growth factor, D polypeptide (PDGFD), TAC4, and VIP." (PMID 35453627, 2022).
mood disorder (1 paper, 2024). A cognitive disorder a disturbance in which the person's mood is hypothesized to be the main underlying feature. "By examining both matrices, this study aimed to provide a robust understanding of apelin’s biological distribution and its potential as a biomarker in mood disorders." (PMID 39769424, 2024). "The observed elevation in plasma apelin levels and their significant correlation with the severity of depressive symptoms provide compelling evidence for apelin as one of the molecular targets to consider in mood disorders." (PMID 39769424, 2024). "Therefore, further investigations are needed to completely explain the role of apelin in the pathophysiology of MDD and its potential as a critical mediator in the interplay between mood disorders and related symptoms." (PMID 39769424, 2024).
morbid obesity (1 paper, 2025). An excess of body weight, normally defined as an individual with a body mass index greater than 35 or a body weight greater than one hundred percent of ideal body weight. "Similar to adiponectin, apelin also improves insulin sensitivity by increasing Akt phosphorylation and glucose uptake via the AMPK pathway, with studies reporting higher apelin concentrations in insulin-resistant and/or individuals with morbid obesity and T2D." (PMID 41376626, 2025).
multiple myeloma (1 paper, 2022). "For instance, cancer patients with disease progression or death within 24 months showed higher serum apelin at baseline, while multiple myeloma patients with higher serum apelin at the time of diagnosis had longer median survival." (PMID 36230579, 2022).
muscle atrophy (1 paper, 2023). The loss of muscle tissue due to inactivity or disease. "This evidence indicates that intervention in the apelin–Apj could be a promising strategy for the treatment of skeletal muscle atrophy and the comprehensive management of CKD." (PMID 36562292, 2023). "In addition to this efficacy, we uncovered new properties of apelin for CKD‐induced muscle atrophy." (PMID 36562292, 2023).
nephrogenic syndrome of inappropriate antidiuresis (1 paper, 2021). "Another application for metabolically stable apelin analogs could be in the nephrogenic syndrome of inappropriate antidiuresis (NSIAD)." (PMID 34880830, 2021).
neuroblastoma (1 paper, 2023). Neuroblastoma (NB) is the most common solid, extracranial childhood tumor. "It is reported that in human neuroblastoma SH-SY5Y cells, apelin reduced calcium release, caspase-3, and cytochrome c, preventing apoptosis, oxidative stress, and mitochondrial toxicity." (PMID 37687017, 2023).
oligodendroglioma (1 paper, 2022). A well-differentiated (WHO grade II), diffusely infiltrating neuroglial tumor, typically located in the cerebral hemispheres. "Our results showed that the significant correlation between elevated APLN expression and inferior OS or RFS in LGG patients was restricted to patients with seizure history, primary tumor, targeted molecular therapy, oligodendroglioma, biopsy, and TMZ therapy." (PMID 36193059, 2022).
osteomyelitis (1 paper, 2026). An acute or chronic inflammation of the bone and its structures due to infection with pyogenic bacteria. "Serum SIRT1, SIRT3, apelin, and ELA levels were significantly lower in the DFI group and showed inverse correlations with HbA1c, PEDIS stage, disease duration, osteomyelitis, and inflammatory markers." (PMID 42195360, 2026).
pancreatitis (1 paper, 2023). Inflammation of the pancreas. "They found a bidirectional, negative feedback loop that targeted the transcriptional regulation of apelin and PTHrP; in particular, the anti-inflammatory and antifibrotic role of BMP2 appeared to be mediated by the concurrent activation of apelin and inhibition of PTHrPsignaling during pancreatitis." (PMID 37508381, 2023).
paraganglioma (1 paper, 2022). A benign or malignant neoplasm arising from paraganglia located along the sympathetic or parasympathetic nerves. "Specificity, sensitivity, positive and negative predictive value of apelin, SDHB and CHGB in differentiating metastatic from non-metastatic pheochromocytoma and paraganglioma." (PMID 35574028, 2022).
Polyuria (1 paper, 2017). An increased rate of urine production. "However, since in NDI AVP is unable to exert its antidiuretic effect at the kidney level, it is likely that only apelin exerts its deleterious effect, which results in polyuria." (PMID 28620355, 2017). "Possibly, the decrease in plasma apelin levels of patients with CDI is insufficient as compared to the decrease of AVP/copeptin to reestablish a balance between the antidiuretic effect of AVP and the diuretic effect of apelin, resulting in polyuria." (PMID 28620355, 2017).
prediabetes (1 paper, 2024). "The analysis suggested that apelin levels might influence the likelihood of prediabetes; however, this association lost significance after adjusting for BMI and HOMA-IR." (PMID 39857634, 2024). "Among the obese participants, 71.1% were diagnosed with prediabetes, and those with prediabetes had markedly lower apelin levels than healthy controls." (PMID 39857634, 2024).
pressure ulcers (1 paper, 2020). "Objective was to assess the role of apelin/APJ signaling in the development of pressure ulcers (PUs) formation after cutaneous I/R injury in mice." (PMID 31992828, 2020).
primary immunodeficiency (1 paper, 2024). "These modules contained pathways such as necroptosis, tight junction, receptor-ECM interaction, apelin signaling, PI3K-AKT signaling, homologous recombination, primary immunodeficiency, pathways in cancer, as well as starch and sucrose metabolism." (PMID 39539669, 2024).
pulmonary diseases (1 paper, 2023). "In recent years, apelin has been found to be associated with several lung diseases 18-22." (PMID 37705751, 2023). "Previous studies showed that apelin was involved in the pathogenesis of several pulmonary diseases, including pulmonary hypertension 18, pulmonary thromboembolism 19, acute lung injury/acute respiratory distress syndrome 20, 21, chronic obstructive pulmonary disease 22, and lung cancer." (PMID 37705751, 2023).
renal carcinoma (1 paper, 2019). A carcinoma arising from the epithelium of the renal parenchyma or the renal pelvis. "Taken together, these results indicate that high Apelin levels in serum samples correlate with worse prognosis of renal cancer patients treated with approved and clinically utilized anti‐angiogenic therapy." (PMID 31267692, 2019).
reno-vascular hypertensive (1 paper, 2018). "In this study, the cardiac effects of two different doses of apelin and the interaction of APJ with OPR in the heart of reno-vascular hypertensive rats were investigated." (PMID 30627376, 2018). "Therefore, it seems that both apelin 20 and 40 exert negative lusitropic effects on the heart of acute reno-vascular hypertensive rats, especially from the third minute." (PMID 30627376, 2018).
retinopathy of prematurity (1 paper, 2022). A bilateral retinopathy characterized by neovascularization, scarring, retinal detachment, and eventually blindness. "Although several clinical studies have analysed the relationship between the levels of vascular endothelial growth factor (VEGF) and apelin-13 in venous blood and retinopathy of prematurity (ROP), no definitive conclusions have been reached." (PMID 35953806, 2022).